CSE1L (chromosome segregation 1 like)
Diseases named in the same sentence as CSE1L in open-access papers (continued):
Sharing a sentence is not in itself a finding about the gene and the disease.
seminoma (2 papers, 2019 to 2023). A radiosensitive malignant germ cell tumor found in the testis (especially undescended), and extragonadal sites (anterior mediastinum and pineal gland). "We also utilized immunofluorescence images to show how CSE1L is associated with mitotic spindles during the TCam‐2 cell cycle and may facilitate seminoma cell division." (PMID 30485574, 2019). "By contrast, in the seminoma tissues, CSE1L was intensely expressed in the nuclear and cytoplasmic areas of the tumour cells." (PMID 30485574, 2019). "CSE1L was significantly enriched in the seminoma tissue compared with the non‐tumour normal testis tissue." (PMID 30485574, 2019). "Semi‐quantitative scores of CSE1L expression in IHC slides showed a dramatic upregulation of CSE1L in the seminoma samples." (PMID 30485574, 2019). "To further determine and compare the CSE1L expression levels between the normal and seminoma tissues, we performed immunochemical analysis in the samples containing both seminoma and non‐tumour normal tissues." (PMID 30485574, 2019). "We further knocked down CSE1L in a seminoma cell line TCam‐2 to investigate CSE1L function in testicular cancers." (PMID 30485574, 2019). "The expression of CSE1L was detected by immunohistochemistry in seminoma tissues and non‐tumour normal testis tissues from patients." (PMID 30485574, 2019). "In the seminoma tissues, CSE1L was expressed in the nucleus and cytoplasm of most tumour cells, but the CSE1L distribution also tended to concentrate in the cytoplasm of some cells and co‐localized with α‐tubulin, as indicated by the white arrowheads." (PMID 30485574, 2019). "Overall, these findings showed that CSE1L plays a pivotal role in maintaining cell proliferation and cell division in seminomas." (PMID 30485574, 2019). "To explore how CSE1L functions in seminoma cancers, we used the seminoma TCam‐2 cells to determine the location of endogenous CSE1L during cell division by immunofluorescence." (PMID 30485574, 2019). "In this regard, CSE1L and PFDN4 could be novel, previously unrecognized cancer-testis antigens, which was partially supported in the case of CSE1L and its role in maintaining cell proliferation and division in seminomas." (PMID 37371576, 2023). "Herein, we found that CSE1L was significantly enriched in seminoma than in non‐tumour normal testis tissues, and this result indicated that CSE1L may play a pivotal role in seminoma tumorigenesis." (PMID 30485574, 2019). "CSE1L was silenced in the seminoma cell line TCam‐2, and the cell growth was inhibited." (PMID 30485574, 2019). "Herein, we found that the CSE1L protein is enriched in human seminoma tissue samples." (PMID 30485574, 2019). "In addition, proliferating cell nuclear antigen (PCNA) was expressed in most cells expressing CSE1L in the testis and seminoma tissues, indicating that CSE1L may be closely related to cell proliferation." (PMID 30485574, 2019). "Overall, we presumed that CSE1L may be highly involved in cell division of seminomas." (PMID 30485574, 2019). "However, whether CSE1L has functions in the seminoma is unclear." (PMID 30485574, 2019).
serous ovarian carcinoma (2 papers, 2010 to 2022). "In serous ovarian carcinoma, moderate to strong immunostaining of CSE1L was observed in 34 of 41 cases (83%) of serous carcinomas, and CSE1L immunoreactivity was positively related to the frequency of apoptotic bodies (p = 0.0170), the tumor grade (p = 0.0107), and adverse outcomes (p = 0.0035)." (PMID 20701792, 2010).
bladder cancer (1 paper, 2024). "Evidence from the Kaplan-Meier plotter and nomogram analyses indicated that CSE1L possesses both diagnostic and prognostic value in distinguishing bladder cancer patients from healthy individuals." (PMID 39430746, 2024). "The overexpression of CSE1L is associated with the progression and poor prognosis of bladder cancer, suggesting it could be a promising target for bladder cancer in the future." (PMID 39430746, 2024). "We found that silencing CSE1L expression in bladder cancer cells inhibited cell proliferation and reduced cell invasion and migration." (PMID 39430746, 2024). "Our study also revealed that CSE1L expression in bladder cancer is correlated with the type and density of infiltrating immune cells." (PMID 39430746, 2024). "However, the clinical significance and biological functions of CSE1L in bladder cancer remain unclear." (PMID 39430746, 2024). "The expression level of CSE1L is upregulated in BLCA cells and is correlated with tumor progression, poor prognosis, and immune infiltration in bladder cancer." (PMID 39430746, 2024).
bladder tumor (1 paper, 2024). "In this study, a series of experiments was conducted to elucidate the biological functions of CSE1L in bladder tumor cells." (PMID 39430746, 2024).
cataract (1 paper, 2021). Partial or complete opacity of the crystalline lens of one or both eyes that decreases visual acuity and eventually results in blindness. "This regulation of Pax6 by Cse1l may explain the early onset cataracts and microphthalmia in Cse1lnull/wt mice, as well as the range of eye abnormalities in the anteater mutants." (PMID 34287339, 2021).
dyslexia (1 paper, 2025). A learning disorder characterized by an impairment in processing written words. "The most significantly associated independent SNPs; rs13082684 (PPP2R3A), rs2426117 (CSE1L) and rs9696811 (located between PTPA and IER5L), were consistent with loci reported in the univariate dyslexia GWAS." (PMID 40825760, 2025).
influenza (1 paper, 2011). An acute viral infection of the respiratory tract, occurring in isolated cases, in epidemics, or in pandemics; it is caused by serologically different strains of viruses (influenzaviruses) designated A, B, and C, has a 3-day incubation period, and usually lasts for 3 to 10 days. "In cells depleted of a subunit of the vATPase (ATP6V1B2) responsible for acidification of endosomes, and CAS (CSE1L), a factor required for nuclear import of influenza vRNPs, infection was almost completely inhibited." (PMID 22046129, 2011).
larynx tumors (1 paper, 2021). "In our study, we tried to find out the relationship between CSE1L expression and cervical nodal metastasis in larynx tumors." (PMID 31383592, 2021). "Our aim was to find out whether there is a correlation between CSE1L expression and regional lymph node metastasis in advanced stage larynx tumors." (PMID 31383592, 2021).
malignant lymphomas (1 paper, 2010). "In normal lymphoid tissue and malignant lymphomas, low-grade non-Hodgkin's lymphoma revealed weak CSE1L staining, with 10% to 60% of all cells positive." (PMID 20701792, 2010).
medulloblastoma (1 paper, 2010). A malignant, invasive embryonal neoplasm arising from the cerebellum. "An array-based comparative genomic hybridization study showed high-frequency amplifications of the CSE1L gene in nasopharyngeal carcinomas and in medulloblastomas." (PMID 20701792, 2010).
metastatic cancer (1 paper, 2010). A carcinoma which has spread from the original site of growth to another anatomic site. "CSE1L actually is a secretory protein associated with cancer metastasis, and CSE1L is more frequently detected in sera of patients with metastatic cancer than with primary cancer." (PMID 20701792, 2010). "Recent studies revealed that CSE1L is a secretory protein, and there is a higher prevalence of secretory CSE1L in the sera of patients with metastatic cancer." (PMID 20701792, 2010). "The results of immunoblotting also showed that secretory CSE1L is present in sera of patients with metastatic cancer." (PMID 20701792, 2010). "Serum samples collected from patients with metastatic cancer were assayed for the presence of secretory CSE1L in sera of patients with metastatic cancer." (PMID 20701792, 2010). "Serum CSE1L was more prevalent in patients with metastatic cancer." (PMID 20701792, 2010). "Therefore, CSE1L is a secretory protein, and there is a higher prevalence of secretory CSE1L in sera of patients with metastatic cancer." (PMID 20701792, 2010). "CSE1L staining in the gland lumen of metastatic cancer tissues indicate that CSE1L may be secreted by cancer tissues and CSE1L may be a secretory protein." (PMID 20701792, 2010). "The presence of secretory CSE1L in the sera of patients with metastatic cancer was not restricted to a specific cancer type." (PMID 20701792, 2010).
metastatic melanoma (1 paper, 2010). A melanoma that has spread from its primary site to another anatomic site. "All metastatic melanomas (n = 23) they studied showed strong CSE1L staining." (PMID 20701792, 2010). "Heavy CSE1L staining was observed in all of the metastatic melanoma (n = 23) they studied." (PMID 20701792, 2010).
microphthalmia (1 paper, 2021). Congenital or developmental anomaly in which the eyeballs are abnormally small. "Here, we present a hypomorphic mutant allele of Cse1l discovered in a forward genetic screen which displays a variable range of neural and ocular phenotypes including microphthalmia and ventral telencephalic defects." (PMID 34287339, 2021).
nasopharyngeal carcinoma (1 paper, 2010). A carcinoma arising from the nasopharyngeal epithelium. "The results of another study using microarray-based detection showed that CSE1L was highly expressed in nasopharyngeal carcinomas." (PMID 20701792, 2010).
non-Hodgkin lymphoma (1 paper, 2010). Distinct from Hodgkin lymphoma both morphologically and biologically, non-Hodgkin lymphoma (NHL) is characterized by the absence of Reed-Sternberg cells, can occur at any age, and usually presents as a localized or generalized lymphadenopathy associated with fever and weight loss. "In contrast, highly malignant non-Hodgkin's lymphoma and malignant cells of Hodgkin's disease displayed very strong CSE1L positivity, with staining of up to 80% of atypical cells." (PMID 20701792, 2010).
prostate carcinoma (1 paper, 2010). A carcinoma that arises from epithelial cells of the prostate gland. "Combined cytogenetic, array-based comparative genomic hybridization studies and expression analyses also showed that CSE1L was significantly overexpressed in advanced prostate cancer xenografts." (PMID 20701792, 2010).
schizophrenia (1 paper, 2024). A major psychotic disorder characterized by abnormalities in the perception or expression of reality. "Other genome-wide significant SNPs are in genes associated with schizophrenia (rs6125539; 4.72 × 10−09; CSE1L) and impulsivity (rs1248860; 9.51 × 10−09; CADM2)." (PMID 38811692, 2024).
squamous cell carcinoma (1 paper, 2021). A carcinoma arising from squamous epithelial cells. "In contrast, nuclear TAZ expression was high in none of CSE1L-low adenocarcinoma and squamous cell carcinoma cases." (PMID 34022224, 2021).
testicular cancer (1 paper, 2019). A primary or metastatic malignant neoplasm that affects the testis. "Despite all these functions of CSE1L reported in multiple types of cancers, the clinical significance of CSE1L in testicular cancer has not been demonstrated." (PMID 30485574, 2019).
viral infection (1 paper, 2022). "We also mapped the regulatory networks of differential lncRNAs and their target genes during viral infection, and found that the cis-acting lncRNA MSTRG.14019.1 targeted CSE1L and may affect virus replication." (PMID 35495687, 2022).
cancer (41 papers, 2010 to 2026). A tumor composed of atypical neoplastic, often pleomorphic cells that invade other tissues. "CSE1L encodes a protein that is involved in various cellular processes and plays a critical role in cancer initiation and progression." (PMID 39430746, 2024). "Multiple potential underlying mechanisms of CSE1L action have been documented in various types of cancer." (PMID 39430746, 2024). "Erbb2-driven carcinomas with Cse1l deficiency outgrow less irregularly from mammary ducts, and NLS-attenuating mutants or variants of HER2 favor escape in 3D culture." (PMID 37055441, 2023). "High expression of CSE1L is associated with a poor prognosis in cancers and is considered to be a prognostic marker." (PMID 34022224, 2021). "Previous documents showed that CSE1L was implicated in tumorigenesis by acting as an oncogenic gene in some cancers." (PMID 30144787, 2018). "Pathological studies have shown that CSE1L is highly expressed in most cancer types, and its expression is associated with advanced cancer stage and poor outcome in cancer patients." (PMID 26070816, 2015). "Cytoplasmic CSE1L was associated with cancer stage (P=0.003) and depth of tumor penetration (P=0.007)." (PMID 23369209, 2013). "CSE1L, the chromosome segregation 1-like protein, is implicated in cancer progression and is located in both the cytoplasm and nuclei of tumor cells." (PMID 23369209, 2013). "Statistical analysis showed that high-CSE1L cytoplasmic staining in a CRC tumor was associated with advanced cancer stage (Stage II, III, or IV) and depth of tumor penetration (T status)." (PMID 23369209, 2013). "CSE1L was previous regarded as a proliferation-associated protein and was thought to be associated with tumor proliferation in cancer progression." (PMID 20701792, 2010). "CSE1L was originally regarded as a proliferation-associated protein and was thought to regulate the proliferation of cancer cells in cancer progression." (PMID 20701792, 2010). "The results of enzyme-linked immunosorbent assay (ELISA) showed that serum CSE1L was detected in 58.2% (32/55), 32.0% (8/25), and 12.1% (8/66) of patients with metastatic, invasive, and primary cancers, respectively." (PMID 20701792, 2010). "Moreover, to investigate the potential mechanism behind the effectiveness of CSE1L in tumor progression, we performed an assessment of the activity of 14 signaling pathways associated with cancer using the R package “PROGENy”." (PMID 40406120, 2025). "CSE1L, the cellular apoptosis susceptibility protein, is highly expressed in various cancers." (PMID 33602168, 2021). "CSE1L is implicated in cell proliferation and apoptosis in human cancers." (PMID 34022224, 2021). "In human cancers, high expression of CSE1L is associated with a poor prognosis." (PMID 34022224, 2021). "CSE1L overexpression was associated with increased invasiveness and metastasis of cancer cells." (PMID 23369209, 2013). "Thus, the association between CSE1L overexpression and the development of polarity and tumorigenicity inhibition observed in HT-29 cancer cells appears to be specific to that cell line." (PMID 23369209, 2013). "CSE1L is a cellular apoptosis susceptibility protein and it is highly expressed in various cancers; our recent studies showed that CSE1L plays an important role in regulating cancer cell apoptosis induced by chemotherapeutic drugs." (PMID 20701792, 2010). "Because CSE1L is highly expressed in various cancers, CSE1L was thus regarded as a proliferation-associated protein and was thought to play a role in tumor proliferation during cancer development and progression." (PMID 20701792, 2010). "Second, CSE1L is associated with mitotic spindles and functions in the mitotic spindle checkpoint; therefore high expression of CSE1L in cancer cells may halt the progression of mitosis until the cells are truly ready to divide." (PMID 20701792, 2010). "Moreover, CSE1L expression is associated with tumor progression in various types of cancers." (PMID 39430746, 2024).
cancer (continued). "Therefore, both nuclear and cytoplasmic CSE1L are implicated in cancer progression." (PMID 23369209, 2013). "The results indicated that most exportin genes had significant amplification events in pan-cancer, with CSE1L being particularly prominent." (PMID 39882192, 2025). "CSE1L has been found to be involved in apoptosis, proliferation, survival, nuclear-cytoplasmic transport, and cancer metastasis." (PMID 39430746, 2024). "The exportin-2 (CSE1L) protein is highly expressed in cancer and regulates invasion and metastasis of cancer cells, being highly related to high cancer stage, high cancer grade, and worse outcomes of patients." (PMID 39194522, 2024). "CSE1L expression was significantly high in cancer samples, with a median level of 6.924 and 6.211 in tumor and normal tissues, respectively (p < 0.001)." (PMID 39430746, 2024). "There are scattered reports of associations between HER2 signaling, nucleocytoplasmic transport, and CSE1L abundance in cancer." (PMID 37055441, 2023). "CSE1L/CAS, a microtubule-associated protein, inhibits PTX-induced apoptosis but enhances cancer cell apoptosis induced by various chemotherapeutic drugs." (PMID 37582832, 2023). "CSE1L (human chromosomal segregation 1-like), which is an effector of apoptosis, invasiveness, and migration of cancer cells, was already found to be related with oral cancer." (PMID 35634436, 2022). "CSE1L is differentially expressed in various malignant tumors and is related to the ability of tumor invasion, metastasis, and proliferation." (PMID 36319976, 2022). "CSE1L (chromosome segregation 1 like) is thought to play an important role in tumorigenesis and acts as a cancer therapeutic target." (PMID 33854580, 2021). "In human cancers, CSE1L confers malignant properties to cancer cells and is regarded as a poor prognostic biomarker." (PMID 34022224, 2021). "We used affinity beads to ascertain a putative target of TI-4, chromosomal segregation 1 like (CSE1L), which is known to be involved in the recycling of importin α and as a biomarker of cancer malignancy." (PMID 34022224, 2021). "As CSE1L regulates mitosis and cell survival, it is considered to be a putative oncogene and is highly amplified in pan-cancers." (PMID 34516344, 2021). "In human cancer tissues, the expression level of CSE1L was found to correlate with nuclear levels of TAZ." (PMID 34022224, 2021). "According to the top 10 signal pathway based on GSEA analysis, we found BAK1 and CSE1L also played positively role in signaling pathway which is relatively correlation with HCC including pathway in cancer." (PMID 33680905, 2020). "CSE1L, also named as CAS (cellular apoptosis susceptibility protein), has been reported as an oncogene in several cancers." (PMID 31139015, 2019). "CSE1L is highly expressed in several cancer types and positively correlates with tumor grade and poorer outcomes." (PMID 28387323, 2017). "Since CSE1L is also secreted from the normal cells in cancer patients, assay of serum phospho-CSE1L is more effective than that using serum CSE1L for cancer diagnosis as well as for the early detection of the efficacy of targeted therapy in patients." (PMID 26070816, 2015). "Our findings suggest that serum phospho-CSE1L has clinical utility in the early detection of the efficacy of targeted therapy as well as monitoring emerging secondary drug resistance in cancer patients, thus facilitating timely treatment decision making." (PMID 26070816, 2015). "The results suggested that serum phospho-CSE1L has clinical application in early detecting the development of resistance to targeted drugs to improve the cure rate of cancer." (PMID 26070816, 2015). "We have previously reported that CSE1L is a secretory protein present in the sera of cancer patients." (PMID 26070816, 2015). "This study showed that for patients with CRC, cytoplasmic CSE1L expression in neoplastic colorectal glands correlated with depth of tumor penetration and cancer stage." (PMID 23369209, 2013).